MALT1 (MALT1 paracaspase)
Diseases named in the same sentence as MALT1 in open-access papers (continued):
Sharing a sentence is not in itself a finding about the gene and the disease.
tumor (continued). "In addition, our findings suggest that inhibition of MALT1-mediated CYLD cleavage, through other BCR signalosome inhibitors such as ibrutinib and sotrastaurin, contributes to the anti-tumor effects of these drugs." (PMID 36922488, 2023). "MALT1 KO in JeKo BTK KD-2 cells did not appear to have an effect on the tumor burden in the spleen or liver, since these cells were already very limited in their quantity at these sites." (PMID 36719376, 2023). "Compared with the negative control group, the tumor volumes in the MALT1 knockdown group were significantly decreased in both two siRNAs." (PMID 35309901, 2022). "We found Malt1−/− mice failed to respond to PD-1 blockade, whereas the therapy can decrease tumor growth in WT mice." (PMID 33963274, 2021). "Importantly, we further analyzed the correlation of expressions between HOXD-AS2 and MALT1, as well as miR-3681-5p and MALT1, in 92 GBM tumor samples." (PMID 34802389, 2021). "In order to determine whether MALT1 also inhibits TIFA-induced apoptosis in vivo, we performed tumor xenograft studies using SK-Hep1-TIFA-shMALT1 cells and SK-Hep1-TIFA-sc cells transplanted into NOD/SCID mice." (PMID 29263897, 2016). "Therefore, we assessed here the simultaneous inhibition of BTK and the protease MALT1 that acts downstream of CARMA1 and is essential for ABC DLBCL tumor growth." (PMID 26540570, 2015). "Importantly, although we showed that MALT1 enzymatic activity is not required for PCa cell survival, it does contribute to PCa tumour cell expression of several proteins that play key roles in PCa development and progression." (PMID 36009554, 2022). "Preventing CARD10 cleavage in the lung tumor A549 cell line increased basal levels of IL-6 and extracellular matrix components in vitro, and led to increased tumor growth in a mouse xenograft model, suggesting that CARD10 cleavage by MALT1 might be a built-in mechanism controlling tumorigenicity." (PMID 33824280, 2021). "Thus, MALT1 appears to be crucial for the maintenance of the proliferative and clonogenic potential of various GBM cell lines, and its silencing or pharmacological inhibition significantly reduces the invasive and migratory potential of the tumor cells both in vitro and in vivo." (PMID 35203553, 2022). "Spearman correlation further showed that there was a significant positive correlation between MALT1 and the expression of HOXD-AS2 in GBM tumor samples, and the expression of miR-3681-5p in tumor tissues showed a negative correlation with MALT1 and HOXD-AS2." (PMID 34802389, 2021). "M1i-124 selectively inhibits NF-κB signaling, cytokine production, and proliferation of MALT1-dependent ABC-DLBCL cells without affecting MALT1-independent GCB-DLBCL cells, promotes selective ABC-DLBCL cell death, and inhibits ABC-DLBCL tumor growth in xenograft models." (PMID 40231473, 2025). "However, MALT1 KO, but not CARD11 KO, showed an additional significant decrease in the tumor cell incidence in BM (P < 0.0001) and PB (P < 0.01)." (PMID 36719376, 2023). "MALT1 KO, but not CARD11 KO, was able to dramatically diminish the tumor growth and dissemination in vitro and in vivo in the resistant MCL cells, supporting our notion that MALT1 hyperactivity critically contributes to IBN resistance via bypassing BTK/CARD11 upstream signaling." (PMID 36719376, 2023). "MiR-26 has been proven to be a multiple tumour suppressor; it does not control IL-6-related inflammation and tumour promoting activity through transcription inhibition but downregulates the production of IL-6 through HMGA1 and MALT1 silencing-induced NF-κB inhibition." (PMID 35864955, 2022).
tumor (continued). "However, others have previously shown that xenograft tumour development was significantly attenuated when tumours were derived from PCa cells lacking MALT1 expression in a mouse model, supporting the role for CBM signalling in tumour formation in a complex microenvironment." (PMID 36009554, 2022).
cancer (39 papers, 2012 to 2026). A tumor composed of atypical neoplastic, often pleomorphic cells that invade other tissues. "Due to this, MALT1 is key in the regulation of inflammatory events in a variety of tissues, where its dysregulation is associated with several types of cancer, especially hematological cancers." (PMID 41557786, 2026). "Dysregulated MALT1 activity is implicated in various lymphoid malignancies, leukaemia and several other cancers including glioblastoma, melanoma, and breast cancer, as well as a large array of autoimmune diseases." (PMID 39014105, 2024). "Mucosa-associated lymphoid tissue 1 (MALT1) acting as a paracaspase in the regulation of nuclear factor κB (NF-κB) signal transduction plays a central role in inflammation and oncogenesis in cancers." (PMID 37047218, 2023). "Mucosa-associated lymphoid tissue 1 (MALT1) is a novel gene involved in nuclear factor κB (NF-κB) signal transduction by acting as an adaptor protein and paracaspase, with an essential role in inflammation and tumorigenesis in many cancers." (PMID 33802402, 2021). "In addition, through GSEA, MALT1 was found to be associated with several cancer-related signaling pathways that promote cancer processes, including NF-κB pathway and Wnt/β-catenin pathway." (PMID 34926571, 2021). "This review systematically analyzes MALT1's oncogenic roles across cancers, clarifies inhibitor mechanisms, and evaluates translational challenges and strategic opportunities for precision oncology and combination immunotherapy." (PMID 41783325, 2026). "This MALT1-TGF-β-NF-κB axis explains TGF-β’s dual role in cancer progression, contributing to survival, proliferation, and metastasis of cancer cells, and highlights MALT1 as a potential therapeutic target for disrupting this interaction in cancer treatment." (PMID 40338274, 2025). "Our whole-transcriptome profiling revealed that apical junction regulation was one of the top cancer hallmarks notably downregulated following MALT1 inhibition." (PMID 36719376, 2023). "This revealed that expression of several cancer-associated proteins, including GM-CSF, CCL20 and VCAM1, was strongly dependent on MALT1 catalytic activity in PC3 cells." (PMID 36009554, 2022). "We next used Human Oncology Array to compare 84 cancer-related proteins in PC3 cells expressing either wild type or catalytically inactive MALT1." (PMID 36009554, 2022). "Small molecule MALT1 inhibitors have already shown promising results in a number of preclinical cancer models for ABC-DLBCL, in which MALT1 is also constitutively activated." (PMID 36009554, 2022). "Previous studies verified that MALT1 is an inductor of NF-κB signaling pathway to promote cancer progression." (PMID 33802402, 2021). "MALT1 is therefore recognized as an oncogene and a promising therapeutic target for cancers highly dependent on NF-κB activaton." (PMID 34802389, 2021). "At this moment, several independent studies have described active site or allosteric MALT1 protease inhibitors, and mouse studies have already indicated the therapeutic value of some of these inhibitors in certain types of cancer and inflammatory diseases." (PMID 31474984, 2019). "Together, our data uncover a segregation of Treg differentiation and suppressive function at the CBM complex level, and provide a rationale to explore MALT1 inhibitors for cancer immunotherapy." (PMID 31138793, 2019). "The CARD–coiled coil (CC)/Bcl10/MALT1-like paracaspase (CBM) signaling complexes composed of a CARD–CC family member (CARD-9, -10, -11, or -14), Bcl10, and the type 1 paracaspase MALT1 (PCASP1) play a pivotal role in immunity, inflammation, and cancer." (PMID 29881386, 2018). "The proteolytic activity of MALT1 was also found to be critical for certain cancers, which has stimulated an interest in MALT1 protease activity as a cancer therapy target as well." (PMID 29881386, 2018).
cancer (continued). "MALT1 is involved in the activation of immune responses, as well as in the proliferation and survival of certain cancer cells." (PMID 29367251, 2018). "All these findings suggest that MALT1 is a promising therapeutic target for the treatment of cancers resulting from NF-κB activation." (PMID 29371921, 2017). "This relationship is supported by correlated expressions of SMAD3 and MALT1 in cancer data (TCGA)." (PMID 40338274, 2025). "Moreover, we demonstrated constitutive MALT1 proteolytic activity in several PCa cell lines, which regulates the expression of several cancer-related genes." (PMID 36009554, 2022). "Therefore, we further focused on PC3 cells to screen for cancer-related proteins that are regulated by the proteolytic activity of MALT1." (PMID 36009554, 2022). "Interestingly, among the identified cancer genes, MALT1 has been recently demonstrated to be involved in the regulation of NF-κB signaling in HTLV-1 mediated leukemogenesis, representing a promising therapeutic target gene for ATL." (PMID 35979358, 2022). "Furthermore, several other studies have identified MALT1 as a central regulator of NF-κB-mediated cancer progression." (PMID 35203553, 2022). "Since the molecular function of MALT1 partially requires its protease activity, pharmacological targeting of MALT1 may represent a promising anti-cancer strategy." (PMID 35203553, 2022). "Therefore, we suggest that MALT1 expression be used as an additional indicator for the evaluation of immunotherapy in cancer patients after treatment." (PMID 34926571, 2021). "Similarly, MALT1 proteolytic activity is essential for the survival and proliferation of certain cancer cells, including ABC-type diffuse large B cell lymphoma and mantle cell lymphoma." (PMID 33083726, 2020). "Future studies should address how MALT1 promotes cellular transformation in various cancers, whether and how specific substrates of MALT1 contribute to tumorigenesis and if MALT1 inhibitors might be of therapeutic interest." (PMID 30214442, 2018). "Studies have focused on the MALT1 paracaspase activity and NF-κB signaling in the immunity of lymphoma, suggesting that dysregulation of this process may result in immune defects, autoimmune diseases, or cancers." (PMID 33802402, 2021). "Therefore, MALT1 has been recognized as an oncogene in cancer progression." (PMID 34802389, 2021). "Therefore, we speculated that MALT1 could impact cancer progression and metastasis by regulating the activity of immune checkpoint genes." (PMID 34926571, 2021). "Therefore, MALT1 may be an emerging therapeutic target for a variety of cancers especially PCa." (PMID 34926571, 2021). "MALT1 expression showed strong correlations with immune checkpoint genes, TMB, and MSI in most cancers." (PMID 34926571, 2021). "We also demonstrated that there is a relationship between MALT1 expression and TMB and MSI in some cancer types and that some tumors show coexpression of MALT1 and major MMR genes." (PMID 34926571, 2021). "In these cancers, MALT1 seems to be activated by constitutive signaling from GPCRs or the EGFR via CARMA3 and/or by overexpression of MALT1 through various mechanisms." (PMID 30214442, 2018). "The paracaspase MALT1 is essential for lymphocyte activation and also plays roles in non-immune cells and cancer." (PMID 42225894, 2026). "Inhibition of MALT1 protease activity did not affect PCa cell survival nor activation of NF-κB and JNK signalling, but reduced expression of cancer-associated genes, including the cytokine IL-6." (PMID 36009554, 2022). "Interestingly, positively correlated loci represented cancer driver genes (MYC, PRKCD, RB1, CDK6), molecules involved in immune response (MALT1, PIK3CG), as well as cellular and hormonal signaling (HGF, PTPN13, IGF1, SMAD1, ESR1, CTGF)." (PMID 34368147, 2021). "Furthermore, we identified Correlation of MALT1 expression with immune check points, TBM and MSI in most cancers by bioinformatic analysis." (PMID 34926571, 2021).
infection (26 papers, 2015 to 2025). The state of being infected such as from the introduction of a foreign agent such as serum, vaccine, antigenic substance or organism. "In future studies it will be interesting to also analyze the effect of MALT1 deficiency on infection with virulent rabies virus or other viruses." (PMID 29367251, 2018). "In the present study, we focused on the impact of MALT1 deficiency on infection with a neurotropic virus." (PMID 29367251, 2018). "MALT1 deficiency is associated with decreased infiltration and activation of inflammatory and immune cells in the brain at the presymptomatic phase of infection." (PMID 29367251, 2018). "IAV-induced MMP-9, TNF, and IL-6 in lungs of MALT1-deficient mice are significantly lower than in wild-type mice after intratracheal infection." (PMID 29018444, 2017). "Interestingly, previous studies illuminate that MALT1 is associated with dysregulated immune response to infection and multiple organic dysfunctions (including kidney injury, lung injury, and liver injury)." (PMID 35262976, 2022). "Consequently, MALT1-deficient mice succumbed to the infection, in sharp contrast to control animals." (PMID 29142134, 2018). "MALT1-deficient mice also have less body weight loss and longer survival after infection." (PMID 29018444, 2017). "RT-qPCR analysis confirmed the significant upregulation of Tnf, Malt1, Nfkb1, and Nfkb2 following infection, consistent with transcriptomic findings." (PMID 40248690, 2025). "In PAMs, MALT1 was significantly induced after infection at an MOI of 0.1 and then downregulated at 48 hpi." (PMID 35467421, 2022). "Intriguingly, in this study, it was found that infection aggravation of PRRSV induced the downregulation of initially elevated MALT1." (PMID 35467421, 2022). "Together, MALT1 acts as an activator in inducing NF-κB activation and proinflammatory cytokine production, while PRRSV-mediated MALT1 downregulation upon infection aggravation avoids aggressive inflammatory responses." (PMID 35467421, 2022). "PRRSV drives MALT1 downregulation upon infection aggravation, which is in absence upon stimulation with other PAMPs, like LPS, implying the unique mechanism on MALT1 from PRRSV is involved in the induction of immune suppression." (PMID 35467421, 2022). "The results showed that over a 36-h infection course, MALT1 was remarkably upregulated both in gene and protein levels." (PMID 35467421, 2022). "The results showed that nsp11 levels were significantly higher than those of nsp6 at 24 hpi, indicating PRRSV manipulates MALT1 expression levels via differential expression of nsps at different stages of infection." (PMID 35467421, 2022). "Intriguingly, 36 h after PRRSV HuN4 infection, a significant decrease in MALT1 protein level was observed in both Marc-145 cells and PAMs." (PMID 35467421, 2022). "Animals lacking malt-1, or harboring the malt-1 protease-dead allele malt-1(C374A), were resistant to PA14 infection compared to N2 controls in both small lawn and big lawn assays." (PMID 32350248, 2020). "Here, we studied infection with an attenuated rabies virus, Evelyn-Rotnycki-Abelseth (ERA) virus, and observed increased susceptibility with ERA virus in MALT1−/− mice." (PMID 29367251, 2018). "Our data demonstrate an important protective role for paracaspase MALT1-mediated signaling in the response to infection with the attenuated rabies virus ERA by mediating neuroinflammation at the early phase of infection." (PMID 29367251, 2018). "Together, our data demonstrate the importance of MALT1-mediated T cell activation to control infection with a live attenuated rabies virus in the brain." (PMID 29367251, 2018). "Antiviral and inflammatory gene expression is severely disrupted in the brain of MALT1−/− mice at the presymptomatic phase of infection." (PMID 29367251, 2018). "Together, these results suggest that at the early stage of infection (10 dpi), antiviral and inflammatory immune responses are severely disrupted in MALT1−/− mice." (PMID 29367251, 2018).